CRP (C-reactive protein)
Diseases named in the same sentence as CRP in open-access papers (continued):
Sharing a sentence is not in itself a finding about the gene and the disease.
diabetes (continued). "CRP/Alb was elevated in diabetes, and FIB-4 was higher in hypertension and hyperlipidemia." (PMID 41302334, 2025). "Furthermore, CRP levels are confounded by comorbidities (e.g., diabetes mellitus) and therapeutic interventions (e.g., antibiotic administration), thereby weakening its causal association with sepsis." (PMID 40703270, 2025). "Risk factors reported were as follows: smoking, body weight, alcohol intake, diabetes mellitus status, C-reactive protein, systolic blood pressure, diastolic blood pressure, pulse pressure, serum cholesterol, serum HDL, LDL, triglycerides, beta-carotene, Vitamin B12." (PMID 39930367, 2025). "Clinical data were collected, including age, D-dimer levels, C-reactive protein (CRP) levels, body mass index (BMI), duration of antibiotic treatment, and relevant medical history (e.g., diabetes, malignancy, the use of corticosteroids, and immunosuppressive agents)." (PMID 40620438, 2025). "Significant differences were observed among the weighted AGP tertile groups in terms of education level, ratio of family income to poverty, smoking history, obesity, total cholesterol, total fiber intake, hs-CRP, history of diabetes, history of hypertension, and prevalence of gallstones (p < 0.05)." (PMID 40013166, 2025). "Elevated levels of serum reactive oxygen species, interleukin (IL)-1, IL-6, tumor necrosis factor (TNF)-α, and C-reactive protein (CRP) have been observed in patients with established type 2 diabetes mellitus (T2DM), indicating their potential role in periodontal tissue destruction." (PMID 40283677, 2025). "In participants with higher levels of inflammation based on CRP, the association between vitamin D deficiency and incident diabetes was not as strong as in participants with lower levels of inflammation." (PMID 39662157, 2025). "CRP, an acute-phase reactant synthesized by the liver in reaction to inflammatory stimuli, has been the subject of substantial investigation in relation to several chronic ailments, including cardiovascular disease, diabetes, and autoimmune illnesses." (PMID 39919114, 2025). "Similarly, diabetes, quantified by HbA1c, directly promotes myocardial fibrosis via advanced glycation end-product deposition, while CRP elevation signifies systemic inflammatory response that accelerates endothelial dysfunction and ventricular remodeling." (PMID 40589454, 2025). "In the case of abdominal obesity, biological risk factors included recent weight gain, hypertension, diabetes, lack of resistance exercise, elevated hs-CRP, and prolonged sedentary behavior." (PMID 40362786, 2025). "Across the CRP strata, patients with higher CRP levels tended to be slightly older and exhibited a greater prevalence of hypertension, diabetes, and smoking history, indicating a consistent pattern of elevated inflammatory burden among those with multiple cardiovascular risk factors." (PMID 41200636, 2025). "Clinical risk indicators followed similar patterns, with higher rates of severe depression (5.2 [4.2-6.1]), hypertension (2.1 [1.0-3.2]), diabetes (3.3 [2.3-4.3]), elevated C-reactive protein (3.9 [2.5-5.2]), and abnormal high-density lipoprotein (HDL) cholesterol (3.3 [2.1-4.5])." (PMID 40831916, 2025). "The elevated CRP levels observed in these groups may be partially attributable to the distribution of diabetes." (PMID 40786290, 2025). "Irrespective of conventional risk factors, increased hs-CRP levels in individuals without apparent symptoms can function as a significant indicator of potential heart attack, stroke, diabetes, and cardiovascular fatality." (PMID 40959697, 2025). "In individuals with either frailty or diabetes the levels of CRP differed." (PMID 41210499, 2025).
diabetes (continued). "The demographic characteristics and baseline parameters of the patients, including age, gender, comorbidities (hypertension and diabetes), smoking history, BMI, blood pressure, heart rate, CRP, fasting blood glucose, platelet count, LDL, HDL, TG, TC, and SAQ score were compared between the groups." (PMID 39944604, 2025). "Probiotic supplementation significantly reduced CRP levels in patients with diabetes." (PMID 40123937, 2025). "Furthermore, various factors such as body mass index, weight loss, cigarette smoking, high blood pressure, alcohol consumption, and diabetes can affect the levels of CRP." (PMID 40114845, 2025). "The CRP/HDL-C ratio had the best diagnostic performance AUC = 0.752 (95% CI: 0.711 ~ 0.794), followed by diabetes duration AUC = 0.672(95% CI: 0.626 ~ 0.719), HbA1c AUC = 0.653 (95% CI: 0.605 ~ 0.701), FPG AUC = 0.636 (95% CI: 0.580 ~ 0.692) and age AUC = 0.557 (95% CI: 0.500 ~ 0.613)." (PMID 40104822, 2025). "In addition, CRP/Alb values were significantly higher in participants with diabetes (Z = −2.097, p = 0.036), whereas FIB-4 scores were elevated in those with hypertension (Z = −3.570, p < 0.001) and hyperlipidemia (Z = −2.490, p = 0.013)." (PMID 41302334, 2025). "The hypothesis of this study was that there would be a strong correlation between the CRP/HDL-c ratio and the risk of HUA among individuals with diabetes or prediabetes." (PMID 40655403, 2025). "Hyperglycemia and dyslipidemia result in the elevated circulating levels of proinflammatory cytokines, such as tumor necrosis factor alpha (TNF-α), interleukin-6 (IL-6), interleukin-1β (IL-1β), and C-reactive protein (CRP) which, in turn, increase the risk of diabetes and vascular complications." (PMID 40004134, 2025). "Among patients in the CAR >0.30 group, there is an increased representation of Black patients, poorer economic status, higher prevalence of smoking and obesity, lower eGFR, higher CRP levels and lower albumin levels, and a higher proportion of diabetes patients." (PMID 40128977, 2025). "In patients with diabetes, an 8-week treatment with dapagliflozin significantly increased the abundance of butyrate-producing bacteria (e.g., Butyricicoccus), along with reductions in C-reactive protein (CRP) and fecal LPS levels." (PMID 41440851, 2025). "A randomized, double-blind, placebo-controlled trial had shown that curcumin supplementation at 1500 mg per day for 10 weeks in patients with type 2 diabetes mellitus significantly reduced high-sensitivity C-reactive protein (CRP) levels compared to the control group." (PMID 40933390, 2025). "Thus, compared with non-obstructed patients, those with obstruction were predicted to stay roughly two days less, after adjusting for age, comorbidities, diabetes, and CRP." (PMID 41517288, 2025). "In the diabetes stratification, Hs-CRP was significantly associated with POD in both non-diabetic patients (OR = 1.634, p = 0.001) and diabetic patients (OR = 3.349, p = 0.004)." (PMID 39958614, 2025). "Further analysis indicated that participants in the top quartile (Q4) of ln HALP were more likely to be male, younger, married, smokers, have higher ALT levels, lower CRP levels, higher total calcium levels, and have a greater likelihood of diabetes compared to those in the bottom quartile (Q1)." (PMID 40904783, 2025). "Chronic low-grade inflammation is implicated in diabetic microvascular complications, but the relationship between circulating high-sensitivity C-reactive protein (hs-CRP) and diabetic retinopathy (DR) in type 2 diabetes mellitus (T2DM) remains incompletely defined." (PMID 41159344, 2025). "Other reports similarly noted that hyperglycemia and diabetes are associated with profound lymphopenia and elevated CRP, IL-6, TNF-α, and PCT compared with non-diabetic patients." (PMID 41156159, 2025).
diabetes (continued). "Univariate logistic regression identified significant risk factors for SSI, including diabetes (P < 0.01), smoking (P = 0.043), alcohol (P = 0.022), BMI (P < 0.001), SLSI (P < 0.001) and various systemic immune-inflammation biomarkers such as, CRP, SII, and AISI (all P < 0.001)." (PMID 40809418, 2025). "Furthermore, the RCS results showed a linear relationship between the CRP/HDL-c and the risk of developing HUA across the entire diabetes and prediabetes population." (PMID 40655403, 2025). "In line with this, our study revealed higher C-reactive protein levels and lower albumin concentrations among diabetic individuals with low GNRI, further supporting the association between inflammation and poor nutritional state in sarcopenic diabetics." (PMID 41393007, 2025). "After adjusting for BMI, fasting glucose levels, diabetes, smoking, and CRP levels, independent of other cardiovascular risk factors, every 1 pmol/L increase in sclerostin levels was associated with a 5.4% increase in the risk of developing PAD." (PMID 40731833, 2025). "A captivating protein with different roles in either physiological or pathophysiological states, CRP is an acute-phase protein, with implications in acute MI, stroke, infections, metabolic syndrome, obesity, heart failure, diabetes mellitus, autoimmune disorders, and various cancers." (PMID 40725102, 2025). "In the multiple logistic regression tests, UAR (odds ratio [OR]: 1.365, 95% confidence interval [CI]: 1.195–1.560, p < .001), CRP (OR: 1.149, 95% CI: 1.072–1.231, p < .001), and diabetes (OR: 2.924, 95% CI: 1.444–5.920, p = .003) were independent predictors of poorly developed CCC." (PMID 38269629, 2024). "Model 2 was adjusted for model 1 + marital status, race, education level, family income, smoking status, drinking status, hypertension, diabetes, stroke, coronary heart disease, BMI, energy consumption, protein consumption, carbohydrate consumption, fat consumption and C-reactive protein." (PMID 37337781, 2024). "PHF and PTF were also positively correlated with the inflammatory marker CRP in the IFG/IGT and T2DM groups, indicating that inflammatory markers may be risk factors for the development of diabetes." (PMID 39021593, 2024). "Association between serum fructosamine and C-reactive protein (CRP), interleukin (IL)-8, and phagocytic function of Escherichia coli in 40 dogs that were either non-diabetic healthy controls (n = 20) or dogs with naturally occurring diabetes mellitus (n = 20)." (PMID 39234180, 2024). "Also, we determined that having high hs-CRP levels was a predictor of diabetes mellitus, as also occurs in the normal population." (PMID 38673472, 2024). "In addition, certain inflammatory biomarkers, including adiponectin, CRP, and interleukin 6 (IL-6), have been correlated with the transition from a prediabetic state to diabetes." (PMID 39839274, 2024). "The analysis of the effects of chia supplementation on CRP in patients with type 2 diabetes mellitus and overweight individuals revealed significant CRP reduction, particularly in those with a 12-week or longer intervention and an intervention dosage of over 35 grams per day." (PMID 39703891, 2024). "Additionally, p-values calculated based on weighting showed statistically significant differences (p < 0.05) between age, education, hypertension, diabetes, physical activity, sedentary behavior, poverty income ratio, C-reactive protein, and stroke." (PMID 39758197, 2024). "Furthermore, CRP >10 mg/L, age, duration of diabetes, Wagner grades 3–5, with cardiovascular disease (CVD), and using insulin were identified as risk factors for malnutrition in diabetic patients." (PMID 39364802, 2024). "After adjusting for age, sex, race, education level, family PIR, hypertension status, diabetes, energy intake and CRP level, the negative associations between OBS and obesity, as well as other segmental body composition parameters, were also stable." (PMID 38751744, 2024).
diabetes (continued). "Of note was the strong association between the inflammatory marker CRP and body weight and BMI in the study participants, which has previously been reported in people with diabetes relative to those without." (PMID 38671852, 2024). "Aneurysm prediction models for TAV patients exhibited mean area under the receiver-operating-characteristic curve (AUC) values above 0.8, with the absence of aortic stenosis being the primary predictor, followed by diabetes and high-sensitivity C reactive protein." (PMID 38508639, 2024). "The variables with the greatest impact on the model were patient age, comorbidities (diabetes mellitus and cerebrovascular disease), functional capacity, and laboratory parameters, notably serum lactate, ferritin, CRP, D-dimer, neutrophil, lymphocyte, and platelet counts." (PMID 39315820, 2024). "Multivariate logistic regression analysis showed that elevated UAR was an independent predictor of inadequate CCC (OR: 1.365, 95%CI: 1.195–1.560, p < .001), along with CRP (OR: 1.149, 95%CI: 1.072–1.231, p < .001) and diabetes (OR: 2.924, 95%CI: 1.444–5.920, p = .003)." (PMID 38269629, 2024). "However, only age, smoking, diabetes, low physical activity, low eGFR, low LDL cholesterol, and high hs-CRP remained significantly associated with higher GDF-15 levels in the multivariable regression analysis." (PMID 39780955, 2024). "CRP serves as a biomarker for assessing inflammation, monitoring disease progression, and predicting the onset of specific conditions, notably cardiovascular disease and diabetes." (PMID 39014451, 2024). "Similarly, we were unable to verify diabetes using HBAIC and given the potential role of inflammation in vascular risk, a peripheral inflammation measure, e.g., C reactive protein, would have been useful." (PMID 38932112, 2024). "Adults with cardiovascular disease and/or diabetes receiving maintenance dialysis with high-sensitivity C-reactive protein (hs-CRP) ≥ 2 mg l−1 at baseline were randomized to receive clazakizumab (2.5 mg, 5 mg or 10 mg, n = 32 per dose group) or placebo (n = 31) every 4 weeks." (PMID 38796655, 2024). "We developed two multivariate models: a baseline model (including age, sex, CRP, hypertension, hyperlipidemia, and diabetes) and a hormone model (that included the testosterone, TMPRRS2 and aromatase levels at admission in addition to the variables in the baseline model)." (PMID 39449074, 2024). "Moreover, our study identified a consistently positive correlation between hs-CRP and depressive symptoms in subgroups categorized by age, BMI, marital status, hypertension, diabetes mellitus, coronary artery disease, and cancer." (PMID 38596631, 2024). "Associations between galectin-3, CRP, and PAD were also reportedin patients with diabetes." (PMID 39076571, 2024). "We developed two multivariate models: a baseline model (including age, sex, CRP, obesity, hypertension, hyperlipidemia, and diabetes) and a hormone model (that included the testosterone, TMPRRS2, and aromatase level in addition to the variables in the baseline model)." (PMID 39449074, 2024). "The study indicates that patients with diabetes, hypertension, or dyslipidemia who also have plantar fasciitis are more likely to have systemic inflammation, as evidenced by a significant correlation between plantar fasciitis and elevated CRP levels." (PMID 38983990, 2024). "First, ours is the largest study to-date to report the diagnostic accuracy of CRP as a triage test for pulmonary TB and our consecutive cohort of outpatients enrolled from five TB endemic countries with diverse TB, HIV and diabetes epidemiology ensures the generalizability of our findings." (PMID 38712173, 2024). "Several expected associations between demographic/clinical parameters and comorbidities were noted, including male sex, hepatitis C virus co-infection, BMI, systemic hypertension, and CRP with diabetes; systemic hypertension and diabetes with kidney disease; and smoking status with lung disease." (PMID 38265411, 2024).
diabetes (continued). "Logistic regression analysis revealed that diabetes mellitus (OR 3.305, 95% CI: 1.866–12.616; p = 0.047), CRP level (OR 1.002, 95% CI: 1.001–1.023; p = 0.044), and IL-6 level (OR 1.045, 95% CI: 1.017–1.063; p = 0.001) were independent risk factors for hypoactive delirium." (PMID 38523173, 2024). "Patient clinical characteristics and data, including age, gender, body mass index (BMI), hypertension, diabetes mellitus, dyslipidemia, smoking status, levels of C-reactive protein (CRP) and interleukin-6 (IL-6), and ischemic symptoms within 6 months before surgery, were collected retrospectively." (PMID 38167983, 2024). "There are conflict results in regard to CRP levels, anti- inflammatory cytokine, in diabetes." (PMID 38504163, 2024). "The features predictive of severity included lactate dehydrogenase, age, absolute lymphocyte count, dyspnea, respiratory rate, diabetes mellitus, c-reactive protein, absolute neutrophil count, platelet count, white blood cell count, and saturation of peripheral oxygen." (PMID 38206673, 2024). "However, we did not observe any relationships between poor prognoses and age, CRP, and diabetes mellitus." (PMID 38707085, 2024). "Age, presence of diabetes and CRP were independent predictors of death." (PMID 38750134, 2024). "In an observational study of non-institutionalized adults with type one and two diabetes, higher HbA1c was significantly associated with higher CRP measured using a standard assay." (PMID 38999806, 2024). "There were significant sex differences for BMI, waist circumference, total energy intake, alcohol consumption, FLI, CRP, education years, hypertension and diabetes regarding men (versus women) showing higher values in all mentioned variables, except for education years." (PMID 38337715, 2024). "One possible biological mechanism for such association is C‐reactive protein (CRP), a nonspecific inflammatory biomarker linked to many conditions, including infection, periodontitis, cardiovascular disease, diabetes, and obesity." (PMID 39563168, 2024). "Medications for hypertension, dyslipidemia, and diabetes management may have mitigated the rise in CRP levels by reducing inflammation." (PMID 39598120, 2024). "Hypervolemic patients were older, more frequently had diabetes, and showed higher CRP levels." (PMID 38612530, 2024). "In contrast, others have demonstrated that the association between CRP and cardiovascular mortality does not differ according to diabetes status." (PMID 38570824, 2024). "Women with PCOS exhibit systemic, low-grade, chronic inflammation, which contributes to an increased risk of coronary heart disease (CHD) and type 2 diabetes mellitus (T2DM) as seen by elevated C-reactive protein (CRP), even irrespective of obesity." (PMID 37768523, 2024). "Individuals in quartile 4 were more likely to be older, female, non-Hispanic white, have smoked less than 100 cigarettes, be free of diabetes and hypertension, have a larger waist circumference, have higher levels of high-sensitivity CRP, and have a BMI ≥ 30 kg/m2 (p < 0.05)." (PMID 39116149, 2024). "After adjusting for age, sex, education, marital status, PIR, smoking, BMI, hypertension, diabetes, asthma, coronary heart disease, stroke, energy, protein, carbohydrates, CRP, and total cholesterol, the CDAI showed an L-shaped relationship with severe headache or migraine." (PMID 39148702, 2024). "Thus, LRG1 stayed predictive for MACE after compensation for hyperlipidemia, diabetes, cTnI, and CRP in patients with STEMI." (PMID 38742172, 2024). "In the present study, we found increased risk of CVD death from mean plasma CRP concentrations above 1.4 mg/L, regardless of diabetes status." (PMID 38730445, 2024).